MYH9 (myosin heavy chain 9)
Diseases named in the same sentence as MYH9 in open-access papers (continued):
Sharing a sentence is not in itself a finding about the gene and the disease.
tumor (continued). "Many studies suggest that MYH9/NMHC-IIA plays a key role in tumor cell invasive behavior; and a recent study shows that the inhibition of MYH9/NMHC-IIA expression can inhibit the metastasis of GC cells." (PMID 24209905, 2013). "Regarding biological functions, let-7f inhibits tumor cell proliferation, invasion, metastasis, stemness maintenance, and metabolic reprogramming by targeting multiple oncogenes (e.g., MYH9, HMGA2, ADAMTS1, Periostin) and key signaling pathways (e.g., MAPK, Wnt, PI3K/AKT)." (PMID 42293764, 2026). "MYH9 promotes tumor stemness by regulating various signaling pathways." (PMID 39988672, 2025). "Furthermore, the elevated expression of MYH9 in certain malignancies suggests its potential as a target for tumor therapy." (PMID 39149512, 2024). "MYH9 significantly influences tumor cell migration and infiltration." (PMID 39149512, 2024). "In BC, several studies have shed light on the roles of MYH9 in tumor metastasis." (PMID 38902769, 2024). "Additionally, we discuss the relationship between MYH9-related diseases (MYH9-RD) and tumors and also summarize tumor therapeutic approaches targeting MYH9." (PMID 39149512, 2024). "The expression levels of MYH9 were notably elevated in the pertinent tumor tissues and exhibited correlations with the clinical stage, histological type, disease progression, and an unfavorable prognosis of the tumor." (PMID 39149512, 2024). "MYH9 is a potent promoter of tumor stem cells that can prompt hepatocellular carcinogenesis." (PMID 39149512, 2024). "To verify the clinical significance of p-MYH9, we measured its expression in 171 HCC and normal adjacent tumor tissues by IHC and found that the p-MYH9 level was significantly upregulated in HCC, which indicates that p-MYH9 is a potential therapeutic target in HCC." (PMID 39300073, 2024). "MYH9 is known to promote tumor development, progression, and radiotherapy resistance." (PMID 39550407, 2024). "Studies have revealed a connection between MYH9 and tumor drug resistance." (PMID 39149512, 2024). "The MYH9 gene was initially identified as a tumor suppressor." (PMID 39273383, 2024). "Additionally, a separate study identified MICAL2, a tumor promoter, as a nucleoplasmic shuttle protein dependent on MYH9 and its C-terminal fragment." (PMID 39149512, 2024). "MYH9 has been observed to be overexpressed in various tumors and plays a role in tumor development." (PMID 39149512, 2024). "Knockdown of Myh9 in WT-Bmal1 cells further modestly increased tumor growth." (PMID 38245503, 2024). "While the question of whether MYH9 functions as an oncogene or a tumor suppressor gene is contingent upon the specific tumor type, additional research is warranted." (PMID 39149512, 2024). "Additionally, blebbistatin treatment inhibited MYH9, resulting in cytoskeleton inhibition, corresponding changes in tumor cell morphology, and disappearance of marginal colocalization of Hsp90, ENO1, and PKM2 in tumor cells." (PMID 38874476, 2024). "In mouse tongue squamous cell carcinoma, MYH9 is essential for maintaining mitotic stability during karyokinesis, and its deletion promotes carcinoma progression, indicating its role as a potential tumor suppressor." (PMID 39273383, 2024). "We then evaluated whether MYH9 depletion could counteract the tumor-promoting role of ACTN1 in HNSCC." (PMID 38057867, 2023). "Interestingly, almost all tumour-associated proteins, including the oncogenes DEK and CHD4 and the tumour-suppressor gene MYH9, were expressed at lower levels in LM4 than in T4." (PMID 36691026, 2023). "Previous studies showed that the MYH9 protein could act as a promoter of tumor stemness that facilitates tumor pathogenesis through the regulation of Wnt-β-catenin-STAT3 signaling, which can further interact with the MET pathway." (PMID 36612298, 2023). "Additionally, the intensities of Ki67 and CD44 staining, enhanced by ACTN1 upregulation, were markedly reduced by MYH9 downregulation in xenograft tumor tissues." (PMID 38057867, 2023).
tumor (continued). "Indeed, the exosome-mediated transport of MYH9 is able to directly promote macrophage migration, resulting in increased macrophage infiltration at the tumor site and, consequently, in cancer cell metastasis formation." (PMID 37947594, 2023). "We confirmed via WB, detection of side-population cells, and tumor sphere formation that the overexpression of MYH9 could save the inhibition of cancer stemness in HCC cells caused by the silencing of TM4SF1." (PMID 37069693, 2023). "Interestingly, we also have confirmed that MYH9 significantly promotes cell tumor stemness, metastasis and chemoresistance by interacting with FOXO1, GSK3β or HBX in NPC and HCC 22,23." (PMID 35414777, 2022). "This tumour suppressive role of MYH9 is enacted through NMHCIIA." (PMID 35125114, 2022). "As MYH9 is functionally associated with sunitinib tolerance in ccRCC cells, we further explored whether MYH9 expression in tumor tissues was involved in the response of patients to sunitinib therapy." (PMID 35318312, 2022). "During the metastatic process, interaction of TUBB4A with MYH9 may protect the nucleus to avoid DNA damage and maintain tumor cell survival through the NF-κB signaling response and activation." (PMID 35589707, 2022). "Furthermore, in tumor tissues, the expression levels of these genes were all correlated with MYH9 expression." (PMID 36139430, 2022). "A previous study indicated that MYH9 has a key role in tumor cell invasion." (PMID 35646686, 2022). "We found that FAM222A-AS1 may function as a tumor promoter by sponging miR-let-7f to protect MYH9 from degradation, promoting the growth and progression of CRC cells in vitro and in vivo." (PMID 35646686, 2022). "Also, MRPL23-AS1 accelerated carcinogenesis and tumor growth via increasing MYH9 by sponging miR-30b in OS." (PMID 34901459, 2021). "The deletion of Myh9 led to the inhibition of tumor cell invasion, but its effects on cell proliferation are different depending on environmental mechanics, i.e., whether the cells are on soft or stiff surface." (PMID 32595503, 2020). "Further, we also examined whether knocking down MYH9 in CRLF1-overexpressing TPC1 cells would affect tumor proliferation and colony formation." (PMID 32982961, 2020). "Using fluorescence microscopy, we found that MYH9 shRNA3-infected cells had loose intercellular connections and a morphology similar to cells undergoing an epithelial-mesenchymal transition 21, 22, which suggests that MYH9 may be a tumor suppressor." (PMID 32685004, 2020). "Furthermore, we confirmed that miR-133a-3p, a tumor suppressor, directly downregulated MYH9 protein expression by binding to its 3’UTR in NPC cells." (PMID 31754475, 2019). "Subsequently, we observed that chemically synthesized cinobufotalin (CB) strongly increased FOXO1-induced DDP chemosensitivity by reducing MYH9 expression, and the reduction in MYH9 modulated GSK3β/β-catenin and its downstream tumor stemness and EMT signal in NPC." (PMID 31754475, 2019). "Furthermore, we found that CB is a promising anti-tumor agent that reduced FOXO1-suppressed DDP resistance by antagonizing the FOXO1-interactive protein MYH9 and its-modulated signals in NPC." (PMID 31754475, 2019). "MYH9 was expressed in the membrane and cytoplasm of some tumor cells." (PMID 25826333, 2015). "MYH9 and MYH10 mutations were identified at a similar frequency in 4–5% of cases, and MYH14 was mutated in 2 tumors, and these mutations tended to be mutually exclusive except in one tumor where co-occurrence of MYH9 and 10 mutations was observed." (PMID 26369831, 2015).
tumor (continued). "Additionally, in some highly invasive tumor cells with high EMT status, Hsp90 could also combine with cytoskeleton‐related proteins such as MYH9 and actin to alter the cytoplasmic distribution of glycolytic metabolic enzyme complexes in tumor cells." (PMID 38874476, 2024). "Hence, we can assume that TM4SF1 may activate the NOTCH pathway via upregulation of MYH9, ultimately promoting tumor stemness in HCC." (PMID 37069693, 2023). "Meanwhile, the expression of MYH9, FN1, LTBP1, CALR and AKAP12 is effective in discriminating HR-NB from LR-NB patients, indicating that these non-invasive biomarkers may be used to detect patients at risk of developing aggressive tumor phenotypes." (PMID 37947594, 2023). "Therefore, we might come to the conclusion that MYH9 acted as an important tumor promoter in ccRCC by promoting tumor proliferation and migration, but the molecular mechanism was not fully elucidated." (PMID 35318312, 2022). "However, tumor research has confirmed that MYH9 can play a dual role in cancer." (PMID 36374212, 2022). "In addition, tumor‐specific Hsp90β, vimentin, and MYH9 are screened as the targets of TAPC‐4." (PMID 36031401, 2022). "Thus, MYH9 expression of tumor could serve as a valuable predictor of the prognosis for sunitinib-treated ccRCC patients." (PMID 35318312, 2022). "Furthermore, overexpressing ATG9B enhanced adhesion of tumour cells to FN, while silencing MYH9 could reverse this phenomenon, even in the presence of MG132." (PMID 34131310, 2021). "Therefore, MYH9 knockdown in immune cells might decrease tumor immunosurveillance and serve as a tumor suppressor." (PMID 32685004, 2020). "Additionally, in vivo experiments showed that circSLAMF6 depletion could inhibit tumor growth by decreasing MYH9 and increasing miR-204-5p." (PMID 32496549, 2020). "Next, we evaluated whether MYH9 reverses CRLF1-induced tumor proliferation in vivo." (PMID 32982961, 2020). "Thus, it is not surprising that MYH9 expression is associated with poorer tumor differentiation in the present study." (PMID 25826333, 2015). "The findings demonstrated that, in contrast to non‐metastatic tumours, both PGK1 and MYH9 were substantially expressed in metastatic tissues, and in recurrent tissues compared to primary lesions." (PMID 40534132, 2025). "MYH9 and MYH10 silencing were also shown to reverse the proliferative effects of LAMC2 overexpression on tumor cells." (PMID 37891404, 2024). "Through its interaction with MYH9, PTGDS modulates the Wnt signaling pathway and exerts a pro-tumor effect." (PMID 39355132, 2024). "In order to prove that ER stress promotes the formation of LAMC2/MYH9/MYH10 complexes, tunicamycin was used to treat tumor cells, and the results showed that the expression of LAMC2, MYH9, MYH10, GRP78 and DRP1 was significantly increased." (PMID 37891404, 2024). "In HCC, NAP1L5 downregulates MYH9 which, in turn, inhibits PI3K/AKT/mTOR signaling, leading to its tumor-suppressive effects." (PMID 39273383, 2024). "A case report on LUAD identified a novel MYH9-RETA fusion and T790M deletion in plasma circulating tumor DNA (ctDNA) following Osimotinib treatment, leading to rapid progression after 5 months and suggesting a potential resistance mechanism." (PMID 39149512, 2024). "In order to clarify the relationship between DRP1 and LAMC2/MYH9/MYH10 complexes, the DRP1 inhibitor Mdivi-1 and Mdivi-1+Tun were used to treat tumor cells." (PMID 37891404, 2024). "In A549, MCF7, and MHCC-97H cells, silencing either MYH9 or MYH10 significantly increased ROS production, reduced mitochondrial membrane potential, and inhibited clonal formation and tumor cell viability." (PMID 37891404, 2024). "MYH9 binds to polymorphic adenoma-like protein 2 (PLAGL2), a downstream molecule regulated by miR-214-3p, to promote tumor development." (PMID 39273383, 2024).
tumor (continued). "MYH9 overexpression can inhibit the PI3K/AKT signaling pathway, leading to increased p-PI3K and p-AKT levels, which in turn participate in tumor cell progression." (PMID 39149512, 2024). "The knockdown of HULC inhibits tumor growth, which highlights the potential significance of targeting the HULC/miR-9-5p/MYH9 axis for GC treatment." (PMID 39273383, 2024). "In parallel, a series of experimental analyses showed that MYH9 and DRD4 contributed to malignant tumor behavior, and these results suggested that MYH9 and DRD4 have potential as therapeutic targets in CC." (PMID 36345155, 2023). "The mechanistic experiments showed that the binding of MYH9 to NAP1L1, a potential promoter of tumor proliferation, inhibited the ubiquitination and degradation of NAP1L1 by recruiting USP14." (PMID 37770914, 2023). "Lymphocyte genes in MM samples which were very downregulated compared to those in HC samples included MYH9, RN7SL2, ACTB, AHNAK and FLNA, which play important roles in cell motility, cell structure, cell migration and tumour metastasis." (PMID 37914759, 2023). "Based on tumor stage features and the expression of the three identified candidate genes, RABGAP1L, MYH9, and DRD4, we developed logistic regression models for the prediction of CRC patient prognosis by ML." (PMID 36345155, 2023). "To conclude, our study posits that DRGs, especially MYH9 and LRPPRC, hold potential as pivotal architects of the tumor immune milieu in OS." (PMID 37892851, 2023). "For the prediction of Chonnam‐COAD DFS prognosis, Model 3 (tumor stage + DRD4) had the highest AUC (0.72 vs. 0.64 ± 0.02), whereas Model 7 (tumor stage + RABGAP1L + MYH9 + DRD4) had the highest F1 score (0.33 vs. 0.3 ± 0.015)." (PMID 36345155, 2023). "Our data demonstrated that ENKUR induced by CB suppresses HCC malignant activities via antagonizing β-catenin/c-Jun/MYH9/USP7/c-Myc-stimulated cell cycle and EMT pathways, which indicated the significance of ENKUR as a tumor suppressor in HCC." (PMID 35414777, 2022). "Then, silencing lnc-MAFG-AS1 expression is found to impede the tumor progression of HCC both in vitro and in vivo by interacting with NM IIA subunits (MYH9, MYL12B, and MYL6)." (PMID 36034393, 2022). "Among the proteins with higher prot_score, ENO1, TUBB3, MYH9 and YBX1 were reported to promote or inhabit tumor progression by interacting with lncRNAs 46-51." (PMID 35541917, 2022). "Mechanistic analysis identified Wnt/β-catenin and its mediated tumor stemness, EMT and c-Jun as positive downstream signaling pathways of MYH9 in HCC development." (PMID 32296025, 2020). "To verify the tumor-suppressive function of GSK3β, we performed TOP/FOP luciferase reporter assays and found that silencing GSK3β antagonized the suppressive effects of MYH9 knockdown on Wnt signaling." (PMID 32296025, 2020). "In a constructed in situ hepatic cancer model, MYH9-silenced Huh7 and HCCLM3 cells displayed a decelerated tumor growth rate, intrahepatic metastasis, and extrahepatic dissemination in nude mice compared with control cells." (PMID 32296025, 2020). "The data showed that CB is a potent anti-tumor agent, and it further increased FOXO1-induced DDP chemosensitivity by antagonizing MYH9, which regulates GSK3β/β-catenin-mediated tumor stemness and EMT signals in NPC." (PMID 31754475, 2019). "Specifically MYH9 and MYL9 were among the few shared MKL-dependent genes in those two tumor types and our compound reduces expression of both (ca. 2–3-fold) in PC-3 cells." (PMID 27600078, 2016).
tumor (continued). "In soft tumor repopulating cells, the limited F‐actin content and requirement for perforin to interact with nonmuscle myosin heavy chain 9 prevent the generation of sufficient contractile force to form pores." (PMID 41377763, 2025). "In addition, the knockdown of Myh9, Cyb5r3, or RPS3A inhibited tumorigenicity and tumor growth in a subcutaneous xenograft tumor model under HFD conditions." (PMID 40470795, 2025). "Additionally, both S609 on FGA and S1943 on MYH9 are phosphorylated by CSNK2A1, a subunit of the protein kinase CK2 which phosphorylates many TFs in tumor cells." (PMID 40453647, 2025). "Myosin heavy chain 9 (MYH9) is a widely expressed cytoplasmic myosin that binds to actin, converts chemical energy into mechanical force by hydrolyzing ATP, and promotes tumor development by participating in cell proliferation, migration, stem cell differentiation, and signal transduction." (PMID 38504374, 2024). "This disengages MYH9 from the cytoskeleton and increases its nuclear levels in EOC cells, which facilitates the transcriptional regulation of CTNNB1 and activation of Wnt/β‐catenin signaling and thereby induces tumor stemness and platinum resistance." (PMID 39488790, 2024). "Circular MYH9 (circMYH9), an intron-derived circular RNA, plays a crucial role in CRC by promoting serine/glycine metabolism and reducing ROS generation to facilitate tumor growth." (PMID 39273383, 2024). "Another study revealed that perforin interacts with non-muscle MYH9 to exert force on the lesser F-actin in tumor regenerating cells (TRCs)." (PMID 39149512, 2024). "Notably, silencing MYH9 significantly attenuates ACTN1's tumor-promoting effects, supporting the notion that ACTN1 drives HNSCC tumorigenesis primarily by boosting MYH9-dependent GSK-3β degradation." (PMID 38057867, 2023). "Finally, we demonstrated that overexpression of GSK3β dramatically suppressed tumor growth, angiogenesis, EMT, and the expression of β‐catenin and MYH9 in animal models generated by SAMD9 overexpressing ESCC cells." (PMID 36757050, 2023). "The results of IHC assay revealed that MYH9 was downregulated in DNAJA4-overexpressing tumours, while PSMD2 expression had no obvious change." (PMID 37875476, 2023). "Moreover, USP7 suppression downregulated c-Myc, thus inhibiting the tumor cycle and EMT signaling in HCC cells transfected with MYH9 plasmids." (PMID 35414777, 2022). "We also found a ZNF750 in-frame insertion in early-passage HCI-001 PDXs but not in later-passage PDXs nor in early- or late-passage PDxOs and a frameshift deletion of MYH9 that was observed in HCI-019 PDxOs but not in the PDXs or human tumor." (PMID 35221336, 2022). "In particular, various reports demonstrated that MYH9 is involved in tumor proliferation, migration, and metastasis, in this study, YY1 and MYH9 may be the upstream and downstream molecule of FGL1, respectively." (PMID 36268014, 2022). "MYH9 was an effective promoter of tumor stemness, which degraded GSK3B and β-catenin destruction complex by ubiquitin-mediated process to induce the downstream tumor stemness phenotype." (PMID 35242279, 2022).